EPHA10 (EPH receptor A10)
Description:
Receptor for members of the ephrin-A family. Binds to EFNA3, EFNA4 and EFNA5.
Synonyms: FLJ16103; FLJ33655; DFNA88
Tractability: Small molecule: an approved drug acts on it; it belongs to a druggable protein family. Antibody: UniProt places it where antibodies can reach, with high confidence; its Gene Ontology location is reachable by antibodies, with high confidence; UniProt predicts a signal peptide or a membrane-spanning region.
Gene: Protein-coding gene on chromosome 1 (37,713,880 to 37,765,133, reverse strand). Ensembl gene ENSG00000183317.
Subcellular location: Cell membrane (Isoform 1); Cell membrane (Isoform 3); Secreted (Isoform 2)
Pathways (Reactome):
Developmental Biology: EPH-Ephrin signaling; EPH-ephrin mediated repulsion of cells; EPHA-mediated growth cone collapse
Gene Ontology:
Molecular function: ATP binding; protein binding; protein kinase activity; transmembrane-ephrin receptor activity
Biological process: axon guidance; ephrin receptor signaling pathway; cell surface receptor protein tyrosine kinase signaling pathway
Cellular component: dendrite; plasma membrane; extracellular region; membrane
Genetic constraint (gnomAD): Loss-of-function variants: 120 observed, 94.31 expected, observed/expected ratio (o/e) 1.27, 90% interval 1.1 to 1.48. The upper end of that interval is the gene's LOEUF score, 1.48, which puts it in group 6 of 6, group 1 being the genes least tolerant of losing a copy. Missense variants: 1,396 observed, 1,284.4 expected, observed/expected ratio (o/e) 1.09, 90% interval 1.04 to 1.14. Synonymous variants: 640 observed, 557.59 expected, observed/expected ratio (o/e) 1.15, 90% interval 1.08 to 1.23.
Homologues: Orthologues: chimpanzee EPHA10 (99% identical), macaque EPHA10 (97% identical), pig EPHA10 (93% identical), dog EPHA10 (93% identical), rat Epha10 (92% identical), mouse Epha10 (27% identical). Paralogues in human: EPHA7 (51% identical), EPHA5 (46% identical), EPHA3 (46% identical), EPHA4 (45% identical), EPHA8 (45% identical), EPHA6 (44% identical), EPHB1 (42% identical), EPHB2 (42% identical), EPHB3 (42% identical), EPHA2 (39% identical), EPHB4 (38% identical), EPHA1 (38% identical), and 41 more.
Diseases named in the same sentence as EPHA10 in open-access papers:
EPHA10 is named in the same sentence as 24 diseases in open-access papers, as found by Europe PMC text mining. Sharing a sentence is not in itself a finding about the gene and the disease. The quoted sentences say what the papers report.
breast carcinoma (16 papers, 2013 to 2024). "Inter-independent genetic profiles reported that the gene amplification of EPHA10 is between 0.8%-17.2% in breast cancer, and a missense mutation in the RTK domain (TCGA data) in 0.2% (5/482) of BC cases." (PMID 28427223, 2017). "Lymph node metastasis in breast cancer was also linked to EphA10 expression." (PMID 36830852, 2023). "Furthermore, immunohistochemistry (IHC) staining of breast cancer tissue microarrays (TMAs) revealed that EphA10 expression at the protein level was also associated with LN metastasis and stage progression (P = 0.016 and P = 0.011, respectively)." (PMID 24403271, 2013). "Overexpression of EPHA10, LYN, and PTK2 (BL1 subtype-specific TK genes) is linked to the severity of breast cancer and can be used as the biomarker for TNBC." (PMID 36672350, 2023). "EphA10 is upregulated in malignant cells, particularly those of the breast and lungs, and reducing its expression in the breast cancer cell line ZR-75-1 resulted in increased apoptosis." (PMID 36830852, 2023). "EphA10 has also been shown to suppress T-cell-mediated death in syngeneic mammary tumours via increased PD-L1 expression." (PMID 36830852, 2023). "Cellular interaction in breast cancer is based on EphA10 and EFNA3 expression, which binds to PD1 on T cells to inhibit immune activity and promote tumor tolerance." (PMID 35945523, 2022). "Surface modification of liposomes with EphA10 antibody enhanced their cellular uptake in breast cancer, enabling active targetability." (PMID 36015212, 2022). "As an example, EphA10 is more highly expressed in breast cancer cells than normal cells and is a unique breast cancer marker." (PMID 36015212, 2022). "Recently, EPHA10 was shown to be overexpressed in breast cancer tissues, and the levels of EPHA10 mRNA and protein were significantly correlated with lymph node metastasis, cancer stage, and tumor progression." (PMID 33436772, 2021). "Antibodies targeting EPHA10 significantly inhibited tumor growth in breast cancer xenograft mouse models." (PMID 33436772, 2021). "We identified a novel therapeutic target that is specifically expressed in the testes of normal tissues and refractory cases of breast cancer (triple-negative breast cancer) called Eph receptor A10 (EphA10)." (PMID 33504115, 2021). "EphA10 expression was also shown to be correlated with breast cancer stage and lymph node metastasis, suggesting that it is a promising target for breast cancer therapy." (PMID 33504115, 2021). "EPHA10 is recognised as potential therapeutic target in breast cancer, but its functional role remains to be characterised." (PMID 28192521, 2017). "Overexpression of EPHA10 protein was reported in concomitance with clinical severity of breast cancer." (PMID 28427223, 2017). "In EPHA10 profile, ROC suggests a strong prognostic value of area under the curve (AUC) as 0.89 (95% CI: 0.86-0.93) in breast cancer prediction (red)." (PMID 28427223, 2017). "Ephrin receptor A10 (EphA10), a transmembrane receptor that binds to ephrin, is a newly identified breast cancer marker protein that has also been detected in HER2-negative tissue." (PMID 26678395, 2015). "Previously, we identified Ephrin receptor A10 (EphA10) as a new human breast cancer biomarker by proteomic analysis." (PMID 26678395, 2015). "Our present findings suggest opportunities for using a BsAb (EphA10/CD3) to treat breast cancer patients whose tumors express EphA10." (PMID 26678395, 2015). "EphA10, originally identified as a breast cancer biomarker, is a cell surface receptor and a specific antigen for cancer tissue, including HER2-negative cases." (PMID 26678395, 2015). "Almost all breast cancer patients are female, and therefore EphA10 targeted therapy is a promising therapeutic strategy for most HER2-negative breast cancer patients." (PMID 26678395, 2015). "Next, it will be necessary to demonstrate the effect of BsAb (EphA10/CD3) against HER2-negative breast cancer derived from patients." (PMID 26678395, 2015).
breast carcinoma (continued). "EphA10 is a novel breast cancer marker that was originally discovered by ourselves using a proteomics approach." (PMID 24403271, 2013). "Here, we have analyzed the expression of EphA10 at the mRNA- and protein-level in clinical breast cancer tissues and then evaluated the relationship with clinicopathological parameters for each sample." (PMID 24403271, 2013). "Using this method, we previously revealed that EphA10 is expressed in many breast cancer tissues compared to normal tissues." (PMID 24403271, 2013). "EphA10 mRNA expression was quantified by real-time polymerase chain reaction using complimentary DNA (cDNA) samples derived from breast cancer patients." (PMID 24403271, 2013). "Eph receptor A10 (EphA10) is a valuable breast cancer marker that is highly expressed in breast cancer tissues by comparison with normal breast tissues, as we previously reported." (PMID 24403271, 2013). "Indeed, EPHA10 deletion in a syngeneic mouse model of breast cancer led to decreased tumor growth and increased CD8+ T cell infiltration." (PMID 36175961, 2022). "Furthermore, EPHA10 has already been approved as a potential therapeutic target of prostate cancer, and high EPHA10 expression correlated with lymph node metastasis of breast cancer —the type of malignant behavior that usually predicts a poor prognosis." (PMID 35495629, 2022). "In order to demonstrate the proof of concept that inhibition of EphA10 specifically expressed in breast cancers induces an anti-tumor effect, we generated a neutralizing monoclonal antibody against EphA10 and then analyzed the therapeutic effect in a xenograft mouse model." (PMID 33504115, 2021). "Our findings demonstrate that BsAb (EphA10/CD3) could potentially be used to achieve potent antitumor T-cell responses in EphA10-positive breast cancer patients." (PMID 26678395, 2015). "BsAb (EphA10/CD3) has two advantages as a potential novel breast cancer therapy." (PMID 26678395, 2015). "Our findings will help elucidate the role of EphA10 in clinical breast cancer progression." (PMID 24403271, 2013). "EPHA10 (the ephrin receptor A10 belonging to the subfamily of receptor tyrosine kinases and involved in cell-cell communication, regulating cell attachment, shape, and mobility in neuronal and epithelial cells), primarily explored in breast cancers, has been recently described in lung cancer." (PMID 33959797, 2021). "In addition, EphA10 was highly expressed not only in breast cancer but also in prostate cancer, suggesting that EphA10 could be a promising target for various kinds of tumors." (PMID 33504115, 2021). "However, the role of EphA10 expression in breast cancer is not well understood." (PMID 24403271, 2013). "In the UALCAN database, the mRNA expression of EPHA1, EPHA10, EFNA1, EFNA3, and EFNA4 was significantly higher, whereas that of EPHA2, EPHA4, EPHA5, and EFNA5 was significantly lower in breast cancer tissues than in paracancerous tissues." (PMID 33977106, 2021). "In breast cancer, ART increased EPHA8, EPHA10, EFNA2 and reduced EPHA3, EPHA7, and EFNA3." (PMID 38630320, 2024). "Together, these results revealed opportunities to redirect the activity of CTL towards tumor cells that express EphA10 using the BsAb (EphA10/CD3), which could be tested in future clinical trials as a novel and potent therapeutic for breast cancer tumors." (PMID 26678395, 2015). "Thus, it should be possible to evaluate the effect of BsAb (EphA10/CD3) both in vitro and in vivo, and results of these studies could predict clinical responses of breast cancer patients who are presently considered incurable." (PMID 26678395, 2015). "In the Immunohistological (IHC) studies, 49% of breast cancer tissues (93/189) and 44% of HER2 negative tissues (60/136) were EphA10-positive while normal breast tissues were negative." (PMID 26678395, 2015).
prostate carcinoma (5 papers, 2018 to 2023). A carcinoma that arises from epithelial cells of the prostate gland. "A recent genome sequence analysis has identified a single nucleotide polymorphism (rs731174) in an intron of the EphA10 gene that may interact with other SNPs to modify prostate cancer risk." (PMID 29682554, 2018). "Ephrin type-A receptor 10 (EPHA10) has been implicated as a potential target for breast and prostate cancer therapy." (PMID 33436772, 2021). "While EphA1 abundance was decreased in prostate cancer cell lines, EphA2, EphA5, EphA6, EphA7, EphA8, and EphA10 levels were elevated in some of the prostate cancer cell lines as compared to the normal prostate cell line." (PMID 29682554, 2018). "An E2F target gene signature, formed by MDX3, PLK1, EPHA10, and KIF4A, exhibited a stronger predictive power than existing signatures in prostate cancer." (PMID 37854038, 2023). "The four gene signatures (MDX3, PLK1, EPHA10, and KIF4A) showed a strong correlation with prostate cancer prognosis in cases selected from TCGA database." (PMID 35495629, 2022).
lymph node metastasis (4 papers, 2013 to 2022). "In invasive samples (n=325), EPHA10 protein is highly expressed in cytoplasm in compared to benign samples (n=76), and in lymph-node metastasis samples (n=50), a significantly additional expression of EPHA10 protein was observed." (PMID 28427223, 2017).
lung carcinoma (3 papers, 2021). "We surveyed 4 datasets from breast, esophageal, and lung cancers and found significantly higher expression of EPHA10 in cancer versus normal tissue." (PMID 33436772, 2021). "For lung cancer, GMPS, EPHA10, C10orf54, and MAGEA6 are highly expressed in different subtypes; for liver cancer, CMYA5, DEPDC6, FAU, VPS24, RCBTB2, LOC100133469, and SLC35B4 are significantly expressed in different subtypes." (PMID 33747053, 2021).
oral squamous cell carcinoma (3 papers, 2022 to 2025). "The present evidence indicates that signaling by EPHA2 and its ligand, EFNA4, promotes hepatocellular carcinoma cell migration and the combination of EFNA4 and EPHA10 promotes proliferation and migration in oral squamous cell carcinoma cells." (PMID 36077763, 2022). "EphA10 was found to regulate EMT and in vitro sphere formation of oral squamous cell carcinoma cells, and promote the occurrence of pancreatic cancers." (PMID 35770949, 2023).
pancreatic cancer (3 papers, 2021 to 2024). "Thus, EphA10 plays a pivotal role in the tumorigenesis of pancreatic epithelial cells and would be a novel therapeutic target for pancreatic cancer." (PMID 39839790, 2024). "EPHA10 silencing reduced the proliferation, migration, and adhesion of MIA PaCa‐2 and AsPC‐1 pancreatic cancer cells." (PMID 39839790, 2024). "In contrast, we identified two RTKs, EPHA10 and ALK, which are associated with a good prognosis in patients with pancreatic cancer regardless of the immune status." (PMID 34479614, 2021).
triple-negative breast carcinoma (3 papers, 2021 to 2022). An invasive breast carcinoma which is negative for expression of estrogen receptor (ER), progesterone receptor (PR), and human epidermal growth factor receptor 2 (HER2). "Cha looks at the expression of the receptor tyrosine kinase ephrin receptor A10 (EphA10), which is undetectable in most normal tissues and at the correlation with tumor progression and poor prognosis in a number of malignancies, including triple-negative breast cancer (TNBC)." (PMID 35885460, 2022).
central nervous system cancer (2 papers, 2016 to 2021). "In contrast, 7 datasets showed markedly lower EPHA10 expression in colorectal, brain, and central nervous system cancers compared to site-matched normal tissue." (PMID 33436772, 2021).
breast tumors (1 paper, 2021). "The present data indicate that EPHA10 is upregulated in BrCa tissues, which is similar with a previous study showing that EPHA10 expression is significantly lower in invasive than in noninvasive breast tumors, and is absent in normal cells." (PMID 33977106, 2021).
cholangiocarcinoma (1 paper, 2024). A carcinoma that arises from the intrahepatic biliary tree (intrahepatic cholangiocarcinoma) or from the junction, or adjacent to the junction, of the right and left hepatic ducts (hilar cholangiocarcinoma). "When examining individual EphA genes like EphA2 and EphA10, significant up-regulation was observed in cases of esophageal carcinoma (ESCA) and cholangiocarcinoma (CHOL)." (PMID 38952552, 2024).
glioblastoma (1 paper, 2024). The most malignant astrocytic tumor (WHO grade IV). "Conversely, EphA2 and EphA10 displayed a down-regulation in kidney chromophobe (KICH) and glioblastoma multiforme (GBM)." (PMID 38952552, 2024).
migraine (1 paper, 2023). "Furthermore, we integrated the plasma proteomic dataset with migraine GWAS data for another PWAS, identifying five more genes (MRVI1, PAPPA, B3GNT8, XCL2, and EPHA10) as potential risk genes." (PMID 37592229, 2023).
myopia (1 paper, 2019). "Ephrin receptor A10 (EPHA10), which we found to be involved in the regulation of susceptibility to myopia, was shown to influence cone photoreceptor morphogenesis, implicating signaling at the level of photoreceptors in refractive eye development." (PMID 31362747, 2019).
osteosarcoma (1 paper, 2014). A usually aggressive malignant bone-forming mesenchymal neoplasm, predominantly affecting adolescents and young adults. "Finally, PDGFRα, Axl, PDGFRβ, RYK, EGFR, EphA2, EphA10 and IGF1-R are key targets of imatinib mesylate in osteosarcoma." (PMID 24599309, 2014).
spina bifida (1 paper, 2022). A congenital neural tube defect in which vertebrae are not fully formed. "There were no shared exonic variants in any known mammalian Eph and ephrin genes (EPHA1–EPHA8, EPHA10, EPHB1–EPHB4, EPHB6, EFNA1–EFNA5, and EFNB1–EFNB3) that fulfilled the MAF < 0.01 criteria in all seven spina bifida probands." (PMID 35741713, 2022).
squamous cell carcinoma (1 paper, 2025). A carcinoma arising from squamous epithelial cells. "ML identified robust predictive models, highlighting SUV and kurtosis (from PET and CT features, respectively) and the expression levels of TP63, EPHA10, FBN2, and IL1RAP as key tools for distinguishing adenocarcinoma from squamous cell carcinoma." (PMID 40192792, 2025).